STAT3 (signal transducer and activator of transcription 3)
Diseases named in the same sentence as STAT3 in open-access papers (continued):
Sharing a sentence is not in itself a finding about the gene and the disease.
melanoma (continued). "In addition, we found that knockdown of TLR4 lowered the protein level but not the mRNA level of STAT3 in melanoma cells." (PMID 32312954, 2020). "In melanoma, GADD45B could interact with other genes like STAT3." (PMID 31681565, 2019). "Molecular drivers of these crosstalks, such as STAT3 and STAT5 signaling pathways, could be targeted to manipulate interactions between melanoma cells and immune cells, to develop therapeutics that coordinately regulate skin cancer and inflammatory and/or autoimmune conditions." (PMID 31569642, 2019). "By contrast, STAT3 was not directly bound on PD-L1 gene promoter in melanoma cells." (PMID 31581535, 2019). "Similarly, removing STAT3 in hematopoietic cells, leads to rapid activation of innate immunity by CpG (a TLR9 ligand), with enhanced activation of macrophages, neutrophils and NK cells and production of IFN-γ, TNF-α, IL-12 to eradicate B16 melanoma tumors." (PMID 31480382, 2019). "Indeed, the anti-cancer and anti-metastatic effects of cholesterol-lowering drugs, such as simvastatin, lovastatin, and pitavastatin, which are mediated through suppression of the AKT and STAT3 pathways, have been shown in HCC, renal cancer, malignant melanoma, and ovarian cancer." (PMID 30321984, 2018). "Stimulation with IGF-1 for 24 h significantly increased the expression levels of STAT3-targeted genes, including survivin, BCL-XL, and MCL-1, while IT pretreatment for 2 h markedly decreased IGF-1-induced survivin, BCL-XL, and MCL-1 expression in human melanoma A375S and A2058 cells." (PMID 27323414, 2016). "When treated melanoma cells with 40 μM apigenin for various durations, the expression levels of phospho-STAT3 were decreased at time dependent manners; while apigenin did not affect the total STAT3 protein expressions at the same concentration." (PMID 26911838, 2016). "Consequently, the here presented data do not support a significant impact of the STAT3 rs4796793 SNP on IFNα efficacy in melanoma patients." (PMID 25593920, 2014). "However, this notion did not translate into the clinical situation as the STAT3 rs4796793 genotype did not correlate with the outcome of adjuvant IFNα treatment in stage III melanoma." (PMID 25593920, 2014). "Nonetheless, the role of STAT3 in anoikis and metastasis in melanoma has not been established yet." (PMID 25216522, 2014). "There are different mechanisms and pathways responsible for anti-melanoma actions of medicinal compounds such as promotion of caspase activity, inhibition of angiogenesis and inhibition of the effects of tumor promoting proteins such as PI3-K, Bcl-2, STAT3 and MMPs." (PMID 25102117, 2014). "However, we did not detect a correlation between SNP genotype and STAT3 mRNA expression for either melanoma cells or for peripheral blood lymphocytes." (PMID 25593920, 2014). "Phosphorylated STAT3 transcriptionally activates PAX3 expression in melanocytes, and the silencing of STAT3 or PAX3 using RNAi was recently shown to inhibit the growth of melanoma cells, particularly in melanoma cells that have acquired resistance to the BRAF inhibitor, vemurafenib." (PMID 24062982, 2013). "However, our data show that silencing of STAT3 expression with siRNA does not affect basal proliferation of human melanoma cells." (PMID 24170218, 2013). "Previous studiessuggest that IL-24 selectively kills melanoma cells via an IL-20 receptor-dependentpathway that is independent of STAT3.In melanoma tumor cells, IL-24 induces IFN-α, which leads to growth inhibitionand apoptosis, possibly involving FAS-FASL and TRAIL interactions." (PMID 22569271, 2012).
melanoma (continued). "Univariate logistic regression analysis revealed that p-STAT3 expression (when defined as a continuous variable) in systemic melanoma metastasis was not predictive for the development of CNS metastasis (HR: 0.994; 95% Wald CI: 0.980 – 1.009; n metastases = 148; p = 0.44)." (PMID 22488042, 2012). "We find that the experimentally observed crosstalk between MITF and STAT3 via PIAS3 in melanocytes is faithfully reproduced in our model, offering mechanistic explanations for this behaviour, as well as providing a scaffold for further studies of MITF signalling in melanoma." (PMID 22316093, 2012). "In conclusion, as inhibitors of p-STAT3 move into clinical trials in patients with melanoma, including those with CNS metastasis, stratification by p-STAT3 should be considered for stage IV melanoma patients who have not developed CNS metastasis." (PMID 22488042, 2012). "On the other hand, our studies indicate that therapeutic treatment of mice with the TLR4/9 agonist complex after inoculation of B16F10 melanoma cells can not reverses tumor cell-induced STAT3 activation, IL-10 expression, and autophagy suppression in the lung tissues." (PMID 21931823, 2011). "Additionally, IL-24 produced from transfected Hek cell supernatants (lanes 6), which will be discussed in more detail below, also induced phosphorylation of STAT3 in HaCaT cells but not in any of the melanoma cell lines." (PMID 18074024, 2007). "Consequently, the interaction of IκBζ with EZH2 and HDAC3 might be the most upstream event regulating IκBζ target genes in melanoma, whereas IκBζ-mediated gene activation derives from the additional presence of EZH2- and HDAC3-activated STAT3 and p65 at single gene promoters." (PMID 40562773, 2025). "Therefore, alantolactone combined MAPKi could dual suppress STAT3 and BRAF/MEK/ERK1/2 pathways, consequently inhibiting the expression of downstream Klf4, Oct4, Sox2 and c-Myc proteins, to enhance sensitivity of resistant melanoma to MAPKi." (PMID 38822350, 2024). "In addition, signal transducer and activator of transcription 3 (STAT3), mitogen-activated protein kinase (MAPK) and phosphatidylinositol 3-kinase (PI3K)/AKT signaling pathways activate the expression of PD-L1 receptor, which contributes to melanoma immune escape." (PMID 38299143, 2023). "Since we observed that both melanoma-derived soluble factors as well as recombinant IL-6 activate the STAT3/SOCS3 pathway in microglia, we asked if IL-6 is present in the of the melanoma cells and whether microglia regulate the secretion of this cytokine from melanoma." (PMID 37296634, 2023). "However, no STAT3 inhibitor has been approved for melanoma treatment." (PMID 32536866, 2020). "Whether parthenolide affects both TLR4 and STAT3 in melanoma has not been reported." (PMID 32312954, 2020). "However, whether the JAK2/STAT3 signaling pathway participates in the proangiogenic switch of CAFs in melanoma microenvironment has not been reported." (PMID 30285793, 2018). "Consistent with our above results, TET2/3, but not TET1, were downregulated in melanoma patients in multiple GEO datasets, and TET3 expression was positively correlated with STAT3 expression." (PMID 36854755, 2023). "We now observed that SHP099 activates STAT3 in HUVEC (5 μM) and BMEC (20 μM), but not in the melanoma B16F10 cell line (20 μM)." (PMID 34102002, 2021). "Taken together, our results suggest that compound 1 induces apoptosis by means of the inhibition of the STAT3 pathway, non-specifically targeting both B-RAF-mutant and WT melanoma cells, with much higher cytotoxicity than the current therapeutic drug PLX-4032." (PMID 30691132, 2019). "On the other hand, FAD104 inhibited the phosphorylation level of STAT3, whereas FAD104 had no influence on the Smad1/5/8 phosphorylation in A375 melanoma cells." (PMID 29180690, 2017). "Compound 1 reduced the phosphorylation of JAK2 and STAT3 in A375 melanoma cells, but had no discernible effect on total JAK2 and STAT3 levels." (PMID 28570563, 2017).
melanoma (continued). "However, whether apigenin affects STAT3 signaling in melanoma metastasis has not been elucidated." (PMID 26911838, 2016). "In melanoma, interplay between TLR4 and STAT3 has never been reported." (PMID 32312954, 2020). "Therefore, we hypothesized that STAT3 siRNA could effectively be delivered via MNs to the deep layer of skin, readily accumulate in the local tumor, targetedly silence STAT3 gene, and directly inhibit the melanoma development without leakage into the systemic circulation for reducing the toxicity." (PMID 29348670, 2018). "LIFr knockdown correlated with STAT3 suppression, but not YAP, suggesting that LIFr activation might stimulate melanoma cell migration through the STAT3 pathway." (PMID 26329521, 2015). "Ultimately the lack of interaction between PRMT5 and cyclin D1 or STAT3, and differences in subcellular localization, suggest that the role of PRMT5 in melanoma may differ from its role in other cancers." (PMID 24098663, 2013). "Our data shows that SOID-8 reduced tyrosine phosphorylation of STAT3 in both dose- and time-dependent manners, and this suppression was mediated through decreased levels of phosphorylation of JAK2 but not c-Src in A2058 and A375 melanoma cells." (PMID 23166634, 2012). "We found that pronounced induction of AR expression occurred in a panel of primary and established melanoma cells already by 48 hours of treatment with DAB and other BRAF and MEK inhibitors, while inhibitors of other key signaling pathways, such as NF-κB, STAT3, and AP-1 exerted no such effect." (PMID 37838724, 2023).
glioblastoma (684 papers, 2008 to 2026). The most malignant astrocytic tumor (WHO grade IV). "Recent literature has shown that FGFR4 can promote glioblastoma and that the Arg388 allele increases STAT3/EMT signaling in other tumors." (PMID 41517303, 2025). "miR-200c was upregulated in pancreatic cancer stem-like cells by garcinol targeting Notch1/Oct4 resulting in a loss of stemness and miR-181 was upregulated in glioblastoma cells by inhibiting STAT3 resulting in reduced migration/invasion." (PMID 41303402, 2025). "In one study, the high expression of CD109 expression has been correlated with increased activity of the STAT3 pathways and causing high proliferation of glioblastoma cells." (PMID 40227788, 2025). "In particular, CuI caused G2/M accumulation in glioblastoma cells by downregulating the downstream targets of STAT3 such as cyclin B1 and cdc2 levels." (PMID 38397437, 2024). "Meanwhile, Ptprd is known as a tumor suppressor that is inactivated and mutated in glioblastoma and other human cancers in addition to its role in presynapse maturation, controlling STAT3 signaling which is involved in a broad range of cell differentiation." (PMID 38736483, 2024). "Chuang and co-workers found a novel STAT3 inhibitor, pacritinib, which overcomes temozolomide resistance via downregulating miR-21-enriched exosomes from M2 glioblastoma-associated macrophages." (PMID 38245798, 2024). "In macrophages associated with infiltrating glioblastoma, STAT3 positively regulates the recruitment of associated macrophages and tumor growth." (PMID 38495483, 2024). "Both these mechanisms result in the sustained upregulation of STAT3 and increased glioblastoma tumorigenicity, and they are linked to a poor clinical prognosis in glioblastoma patients." (PMID 38727267, 2024). "The overexpression of CEACAM1-L in glioblastoma-initiating cells has been associated with increased tumorigenesis through the activation of the STAT3 signaling pathway." (PMID 37691945, 2023). "Exosomal STAT3 derived from glioblastoma stem cells traverses the monocyte cytoplasm, causes a molecular change of the actin cytoskeleton, and induces monocytes to polarize toward the tumor-promoting M2 phenotype." (PMID 37012233, 2023). "For instance, STAT3 and C/EBPβ as master regulators of MT were associated with increased tumour infiltration and glioblastoma recurrence." (PMID 35851726, 2022). "The oncoprotein STAT3 that is frequently overactive in glioblastoma cells is associated with more aggressive disease and decreased patient survival." (PMID 35053502, 2022). "Here, we present a novel pro-death function of the oncoprotein STAT3, which is frequently overactivated in multiple human cancers including glioblastoma and is associated with the most aggressive mesenchymal subtype." (PMID 35053502, 2022). "For example, constitutive PI3K activation leads to STAT3-Y705 phosphorylation through TEC family non-receptor tyrosine kinases, and PTEN loss is correlated with TEC-dependent STAT3 activation in glioblastoma." (PMID 35803738, 2022). "obtained tumor samples from 90 patients with glioblastoma (GBM) to examine the association between p‐STAT3 expression levels and patient outcomes." (PMID 35356799, 2022). "CD109 increased the levels of p-STAT3 in keratinocytes and promoted the formation of lung adenocarcinoma metastasis via JAK/STAT3 pathway whereas in glioblastomas such association has remained unexplored." (PMID 33986188, 2021). "The analysis of these groups revealed significant association between CD109 expression and p-STAT3 (P = 0.002) and Ki-67 (P = 0.041) only in glioblastomas." (PMID 33986188, 2021). "In glioblastoma-infiltrating tumor-associated macrophages, STAT3 acts as a positive regulator of aryl hydrocarbon receptor (AHR) and thus increases the recruitment of tumor-associated macrophages and tumor growth." (PMID 32972405, 2020).
glioblastoma (continued). "In glioblastoma patients, tumor-infiltrating macrophages were shown to be predominantly STAT3-positive M2 macrophages, which are associated with a poor prognosis." (PMID 31480382, 2019). "In contrast, high levels of phosphorylated STAT3 is associated with reduced survival rates in glioblastoma and renal cancer, which independently corroborates our findings on the tumor-promoting effects of JAK-STAT signaling in these cancer types." (PMID 31684858, 2019). "Our data are in line with those of previous studies reporting that an increase of Stat3 level associates with a poor prognosis in glioblastoma patients, highlighting the clinical value of Stat3 evaluation for patients with glioblastoma." (PMID 31690341, 2019). "Of note, increased expression of IL-6, IL-6 receptor or activated (phosphorylated) STAT3 correlated with poor survival of glioblastoma patients, and so does loss of the IL-6 negative regulator SOCS3." (PMID 29601503, 2018). "Our recent report demonstrated that BIS is linked to glioblastoma stemness by stabilization of the signal transducer and activator of transcription 3 (STAT3)." (PMID 28642874, 2017). "Further exploration into the mechanistic function of PTPRD in glioblastoma demonstrated that the loss of PTPRD led to the accumulation of active phospho-STAT3 in a p16Ink4A−/− mouse model." (PMID 26474282, 2015). "STAT3 is a tumor suppressor in PTEN-deficient glioblastoma tumors but has a promoting function in EGFRvIII-expressing tumors." (PMID 25965832, 2015). "STAT3 has been suggested to be one of the most important downstream signaling partners of EGFRvIII in tumorigenesis, and many studies have implicated EGFRvIII-STAT3 signaling in the progression of glioblastoma." (PMID 25992628, 2015). "Konnikova and associates have demonstrated that STAT3 regulated the expression of hTERT in human glioblastoma and primary cells." (PMID 24386318, 2013). "In a previous study it has been reported that reactivation of Stat3 in PTEN-deficient glioblastoma cells inhibits their proliferation and invasiveness." (PMID 19587783, 2009). "Furthermore, expression of several genes associated with glioblastoma (STAT3, PDGFRA, MET, and NF1) and neuroblastoma (GATA3, ISL1, LMO1, and LIN28B) progression was downregulated at the transcriptional level in differentiated cells." (PMID 39859209, 2025). "Additionally, TMEM158 has been demonstrated to be associated with the enhancement of proliferation of glioblastoma cells through the STAT3 signaling pathway." (PMID 39428922, 2024). "However, STAT3 has also been implicated in the renewal of NPCs, supporting a dual role in glioblastoma development." (PMID 38339245, 2024). "Overactive STAT3 is implicated in tumor growth and chemoresistance in glioblastoma." (PMID 39769099, 2024). "In addition, TSPAN6 interacted with CDK5 kinase regulatory-subunit associated protein 3 (CDK5RAP3) and regulated STAT3 signaling pathway in glioblastoma." (PMID 38725860, 2024). "In glioblastoma, STAT3 activation is frequently linked to poor prognosis and chemoresistance." (PMID 39769099, 2024). "Numerous studies demonstrate that curcumin can target signaling pathways involved in glioblastoma development: for example, by modulating the activity of transcription factors such as NF-κB and STAT3 and regulating the expression of genes implicated in malignant transformation and cell survival." (PMID 38276486, 2023). "Furthermore, we demonstrated that the inhibition of JNK and STAT3 increased the susceptibility of TMZ-resistant glioblastoma cells to TMZ treatment." (PMID 37759808, 2023). "Moreover, glioblastoma associated microglia/macrophages up-regulate expression of the proinflammatory cytokine interleukin 11 (IL-11), resulting in activation of the STAT3-MYC pathway in GBM cells." (PMID 36555253, 2022). "Phosphorylation of STAT3 is associated with poor clinical outcome of glioblastoma patients." (PMID 36362294, 2022).